ALB (albumin)
Diseases named in the same sentence as ALB in open-access papers (continued):
Sharing a sentence is not in itself a finding about the gene and the disease.
Stroke (continued). "On the other hand, if the released In-111 tagged with albumin and accumulated to the site of stroke, we should have seen higher uptake in animals that received In-111-oxine only." (PMID 23217090, 2012). "By contrast, pre-clinical and clinical data indicate improved neurologic outcomes in patients with stroke who were treated with albumin." (PMID 22507553, 2012). "The contrasting effects of albumin in stroke and TBI reflect the complexity of the cellular responses to MMP-9." (PMID 22507553, 2012). "Animal models of traumatic brain injury, intracortical hematoma, and stroke indicate a neuroprotective role for albumin." (PMID 22507553, 2012). "Other variables significantly associated with mortality in this study included age, stroke, history of malignancy at baseline, a higher CACI, lower mean albumin, higher mean ferritin, lower levels of uric acid and lower body weight." (PMID 21569355, 2011). "In conclusion, ALB acts as a key protective factor in stroke through nutritional support, antioxidant activity, and inflammation modulation, serving as an independent biomarker for assessing tissue damage, predicting prognosis, and guiding personalized clinical interventions." (PMID 41517762, 2026). "However, a recent large-scale prospective study involving 5,111 stroke patients revealed a unique U-shaped relationship between serum albumin and neurological functional outcomes." (PMID 41432712, 2026). "There is a correlation between high albumin levels and improved functional recovery and decreased mortality in stroke patients, which suggests that some neuroprotective effects may be present." (PMID 39935611, 2025). "Epidemiological evidence indicates that low serum albumin levels are linked to incident ischemic heart disease, heart failure, atrial fibrillation, stroke and venous thromboembolism, independent of traditional risk factors, body mass index and inflammation." (PMID 40604420, 2025). "Low serum albumin is linked to increased risk and poorer outcomes in cardiovascular disease, including heart failure, stroke, and coronary artery disease, independent of traditional risk factors." (PMID 40384966, 2025). "In addition, as an essential protein with anti-inflammatory, antioxidant and antithrombotic properties, ALB levels are also closely related to cardiovascular disease and stroke prognosis." (PMID 40371078, 2025). "Of the 82,298 participants initially considered, 52,119 had complete data and no history of stroke, albumin, or globulin deficiency, which were included in the analysis." (PMID 40070476, 2025). "In line with these beneficial roles, population-based research has consistently connected lower serum albumin concentrations to heightened risks for several cardiovascular disorders, such as ischemic heart disease, atrial fibrillation, stroke, heart failure, and venous thromboembolism." (PMID 41536368, 2025). "Similarly, a meta-analysis encompassing 23,597 patients confirmed that low admission albumin levels were significantly correlated with increased long-term mortality following stroke." (PMID 41180526, 2025). "However, they reported relationship between both hematocrit and albumin, and stroke outcome in their study." (PMID 41541867, 2025). "Adjusting albumin levels to this range could potentially reduce the incidence of perioperative stroke." (PMID 40106818, 2025). "Additionally, serum albumin levels are recognized as an important biomarker of stroke treatment outcomes." (PMID 40732927, 2025). "In addition to elevated inflammatory markers, patients with severe stroke showed lower levels of triglycerides and serum albumin." (PMID 40606131, 2025). "Comorbidities such as stroke, acute myocardial infarction, cancer, and hypothyroidism were similar among the HbA1c groups, as were hemoglobin, glucose, urea, creatinine, sodium, chloride, phosphate, albumin, cholesterol, and triglycerides." (PMID 40352967, 2025).
Stroke (continued). "An Italian investigation, performed on 125 stroke subjects, revealed that reduced W levels were positively correlated with depressed ALB and HGB concentrations, with a tendency showing the lowest W levels in stroke patients suffering from the worst nutritional states." (PMID 40806089, 2025). "This study evaluated whether oral amino acid (AA) supplementation with prevalently essential amino acids (EAAs, 82.1%) could improve inflammation and albumin levels in post-stroke patients undergoing neurorehabilitation." (PMID 41003011, 2025). "Herein, an albumin‐specific tagged near‐infrared‐II (NIR‐II) probe is engineered as a chromophore to construct fluorescent proteins (FPs) in situ for assessing BBB disruption in stroke." (PMID 39999308, 2025). "A study from the NHANES database involving 17,303 participants identified a negative correlation between serum albumin levels and stroke risk." (PMID 40491586, 2025). "This study systematically integrated multidimensional clinical indicators including stroke subtype, age, albumin levels, white blood cell count, and ADL scores to construct a validated predictive nomogram for PI risk stratification in stroke rehabilitation patients." (PMID 40994717, 2025). "We explored the association between serum albumin levels and various conditions, including heart failure (HF), venous thromboembolism (VTE), stroke, atrial fibrillation (AF), coronary artery disease (CAD), type 2 diabetes (T2DM), and pulmonary heart disease (PHD)." (PMID 38580915, 2024). "They found that serum albumin levels were significantly higher in patients with moderate or slight dependency compared to those with total or severe dependency at the third month post-stroke (p = 0.008)." (PMID 40655892, 2024). "Furthermore, the Neutrophil Percentage-to-Albumin Ratio (NPAR) has recently gained attention for its significant role in predicting post stroke complications and mortality of stroke patients." (PMID 38361641, 2024). "Recently, glycated albumin has also been analyzed for its usefulness in strokes and TIA diagnosis." (PMID 38256577, 2024). "The relationship between serum albumin levels and severe limitations in ADLs among stroke patients remains unclear." (PMID 39835151, 2024). "In recent years hemoglobin, albumin, lymphocyte, platelet index (HALP), calculated by the formula Hemoglobin (g/dL) × Albumin (g/dL) × Lymphocyte 103/uL/Platelet 103/uL, has been used to determine the prognosis of multiple tumors, heart failure (HR) and stroke." (PMID 39555199, 2024). "Furthermore, owing to its anti-inflammatory effects, albumin served an essential role in stroke therapy." (PMID 38699426, 2024). "Serum albumin levels have been shown to be a predictor of stroke outcomes." (PMID 38794724, 2024). "The role of serum albumin as a prognostic biomarker in this context is an emerging field of study that could yield valuable insights into the post-stroke prognoses of patients." (PMID 38846203, 2024). "Albumin was lower in patients with stroke (p < 0.001) or fractures (p < 0.001) than in volunteers." (PMID 38644839, 2024). "There are three possible mechanisms by which albumin enhances daily mobility after stroke." (PMID 39835151, 2024). "Model 3 represents the fully adjusted model, which accounted for a plenty of confounders such as age, sex, WC, BMI, SBP, DBP, current smoking and drinking habits, education level, physical activity, Hcy, TC, LDL-C, AST, ALT, TBiL, DBiL, Albumin, eGFR, stroke, and usage of antihypertensive drugs." (PMID 39665019, 2024). "Association between serum albumin and severe impairment of ADL among stroke patients." (PMID 39835151, 2024). "Further investigation is required to conclusively establish whether the injection of human albumin can improve stroke patients' clinical outcomes." (PMID 38846203, 2024).
Stroke (continued). "Finally, the cross-sectional nature of our study limits our ability to establish a causal relationship between serum albumin and severe ADL impairment after stroke, which requires further investigation through longitudinal studies." (PMID 39835151, 2024). "However, the association between serum albumin and severe ADL impairments in stroke patients has yet to be investigated." (PMID 39835151, 2024). "A low albumin level on admission may reflect low nutritional status before stroke onset, and it has also been observed as a relevant factor in predicting the resumption of oral intake in patients with subacute stroke." (PMID 38558178, 2024). "Furthermore, we also aimed to quantify current evidence by conducting a focused systematic review and meta-analysis of albumin levels and clinical stroke outcomes." (PMID 38794724, 2024). "Elderly stroke patients with severe hepatic and renal impairment may experience reductions in hepatic and renal blood flow rates, albumin levels, hematocrit values, as well as protein abundance levels of UGT2B7." (PMID 39771574, 2024). "Scientists want to enhance our capacity to detect individuals at elevated risk, customize treatment approaches, and ultimately improve the quality of life for those affected by ischemic stroke by investigating the correlation between serum albumin levels and stroke outcomes." (PMID 38846203, 2024). "Glycated albumin (GA) is a biomarker monitoring glycemia 2–4 weeks before stroke onset." (PMID 39264001, 2024). "Despite this, the significant results observed in this study are consistent with previously published research, indicating that serum albumin levels may play a significant role in predicting stroke severity and outcomes." (PMID 40655892, 2024). "Additionally, albumin’s antioxidant characteristics help counteract oxidative stress, a pivotal factor in stroke pathophysiology and severity." (PMID 38361641, 2024). "Similar to our study, they concluded that lower serum albumin levels were associated with greater functional dependency at three months post-stroke, though the association was not significant at the seventh day." (PMID 40655892, 2024). "A multivariate logistic regression model investigated serum albumin levels and stroke." (PMID 37682189, 2023). "According to a meta-analysis of data from the third Chinese National Stroke Registry, the prognosis was consistently worse over the 3-month follow-up for every 10 g/L decrease in blood albumin [adjusted OR 1.17, 95% CI (1.01, 1.35); adjusted HR 1.86, 95% CI (1.30, 2.64)]." (PMID 37682189, 2023). "Also, the nasogastric feeding was another preferable option to improve the albumin in elderly patients, especially in patients with decline in cognition after stroke, dysphagia and so on38." (PMID 37528213, 2023). "Serum albumin offers neuroprotective effects through antagonizing thrombosis, stagnation and leukocyte adhesion within the postcapillary microcirculation in the early reperfusion phase of stroke." (PMID 36969491, 2023). "While it has received more attention, the connection between albumin levels and the risk of stroke has not yet been thoroughly understood." (PMID 37682189, 2023). "A previous study found that serum albumin levels may change during the first few days after a stroke." (PMID 36794538, 2023). "Patients who experienced delirium were older, had lower body mass index, suffered more previous stroke, had lower preoperative serum albumin, were more frequently admitted to ICU with intubation, and received less low-dose dexmedetomidine when compared with those who did not." (PMID 37051569, 2023). "The albumin to globulin ratio reflects stroke recovery through nutritional and inflammatory status." (PMID 36794538, 2023). "Relationships of the serum albumin level (ln transformation) with stroke in subgroups." (PMID 37682189, 2023). "It shows that sham or the CL hemisphere of stroke brains displayed minimum albumin infiltration." (PMID 38107410, 2023).
Stroke (continued). "Persons in the highest quartiles of YKL-40 were less likely to be of Black race, had lower education, were less likely to have a history of heart failure, and were more likely to have a history of CHD and stroke and to have higher urine albumin-to-creatinine ratios." (PMID 37533144, 2023). "In addition, BMI, DII, albumin, stroke history, and direct HDL-cholesterol level are also predictors of cognitive impairment." (PMID 37179565, 2023). "According to the data from the Third China National Stroke Registry (CNSR-III), low baseline serum ALB levels (<3.5 g/dL) arose as a risk factor associated with poorer outcomes and mortality in acute ischemic stroke (AIS) or transient ischemic attack (TIA) patients at 3-month follow-up." (PMID 37762957, 2023). "The PNI at baseline has been associated with age, male sex, smoking, clinical characteristics (hypertension, atrial fibrillation, previous stroke, and anemia) and nutrition-related factors such as BMI, total cholesterol, albumin, lymphocyte count, and hemoglobin concentration." (PMID 36771390, 2023). "Several studies have indicated a correlation of elevated fibrinogen to albumin ratio and poor outcome and the presence of adverse events in patients with cardiovascular diseases, cancer, venoarterial extracorporeal membrane oxygenation, and stroke." (PMID 35887976, 2022). "Serum albumin is a multifunctional protein that plays important neuroprotective roles in stroke." (PMID 36432473, 2022). "Interestingly, ZT-1a-treated stroke brains exhibited restored retention of albumin immunoreactive signals in the ChP vessels, as seen in Sham brains, and less in the CPECs." (PMID 35413993, 2022). "The serum ALB level is an independent nosocomial pneumonia predictor in stroke patients." (PMID 35748095, 2022). "Most stroke units in China measure serum albumin levels upon admission." (PMID 35807878, 2022). "Results of the present study demonstrate that Storax alleviates brain injury of cerebral ischemia rats at 24 h after stroke, inhibits Albumin-Alexa594 leakage from BBB to the brain parenchyma, and attenuates the ultrastructural disruption of BBB at 6 h after stroke." (PMID 35873558, 2022). "Serum albumin levels have been found to be inversely correlated with stroke incidence and outcome, but the majority of this work only investigated ischemic strokes, but a few reports found that serum Albumin levels can predict hemorrhagic stroke with negative correlation." (PMID 36077089, 2022). "In the present study, the RDW/albumin ratio cut-off value at postoperative day 1 to predict 90-day mortality was 6.8, which was higher than those in other reports (4.59 in acute respiratory distress syndrome cohorts and 4.94 in post-stroke patients)." (PMID 35097135, 2022). "Fasted blood concentrations of vitamins B1, B2, B6, A, D, and E, selenium, choline, coenzyme Q10, albumin, pre-albumin, transferrin, docosahexaenoic acid, and eicosapentaenoic acid were all lower in stroke patients compared to their matched healthy reference subjects, irrespective of OD status." (PMID 36703642, 2022). "The beneficial effect of increased blood albumin in coronary artery disease, HF, AF, stroke and other CVD may primarily refer to its antioxidant, anti-inflammatory, antiplatelet aggregation and electrophysiological activation." (PMID 35850629, 2022). "Another novelty of our study is that we identified that the DIBIL ratio was closely associated with all-cause death in different subgroups divided by age, BMI, systolic blood pressure, heart rate, previous stroke, hemoglobin, HbA1c, albumin, ALT, eGFR, LVEF, LM or three-vessel involved." (PMID 36357834, 2022). "The second explanation may be owing to the neuroprotective effect of high albumin and low LDH levels, which may indirectly influence the risk of SAP by improving the severity of stroke." (PMID 34604286, 2021). "The study shows the importance of albumin level while treating stroke patients." (PMID 33959442, 2021).
Stroke (continued). "Albumin is an important antioxidant that may exert neuroprotective effects on stroke through antioxidant activity and anti-inflammatory activity." (PMID 34604286, 2021). "Albumin was measured mostly in patients with stroke dysphagia." (PMID 33673581, 2021). "Glycated albumin (GA) reflects glycemic variability within 4 weeks of stroke onset, so GA could be a useful marker for predicting prestroke glycemic variability." (PMID 32373074, 2020). "In addition, adjusted multivariate logistic regression analysis showed that only two variables, namely, serum albumin level and stroke history, significantly predicted the presence of PLLCT." (PMID 33260480, 2020). "In addition, older patients with lower albumin levels and preexisting strokes should be checked for the presence of pneumonia despite a negative CXR finding for an active lesion." (PMID 33260480, 2020). "On the basis of this evidence, a recent ESICM consensus on fluid therapy in neurointensive care recommended the use of crystalloids as preferred maintenance fluids in brain-injured patients and avoidance of high-dose (20–25%) albumin during the acute phase of stroke." (PMID 33013661, 2020). "In addition, older patients with a lower albumin level and a preexisting stroke should be checked for the presence of pneumonia despite a negative CXR finding for an active lesion." (PMID 33260480, 2020). "In-hospital mortality and postoperative stroke rates and lengths of intensive care unit stay were similar between the groups; in contrast, in the heparin-albumin-coated group, patients had significantly better outcomes for hospital stay, drainage, and need for erythrocyte transfusion." (PMID 33306317, 2020). "Therefore, this randomized controlled clinical trial was conducted to examine the effects of ALA supplementation on serum albumin, and inflammatory and oxidative stress markers in stroke patients." (PMID 32373498, 2020). "Interestingly, in subarachnoid hemorrhage, a subtype of stroke, albumin treatment attenuated activation of the immune response in parenchymal macrophages of the central nervous system." (PMID 32733451, 2020). "Since we initiated rFGF21 treatment 6 h after stroke, BBB extravasation based on using two tracers with different molecular weights (3 kDa TMR-dextran and Evans blue dye, which is approximately 68 kDa after binding with albumin) was examined 48 h after stroke in this study." (PMID 32012810, 2020). "However, albumin infiltration was observed in the ischemic core area in the T2DM-stroke brains, and the albumin density was significantly decreased in the L-4F treatment group compared with MCAo-control group (p < 0.05, n = 11/group)." (PMID 31708728, 2019). "To determine if blood–brain barrier permeability changes could contribute to preferential localization of melanoma, we stained brain sections for endogenous albumin extravasated at days 1 and 7 after stroke." (PMID 31024232, 2019). "In this novel model we have determined the temporal profile of ICP, showing that ICP peaks at 5–6 days following stroke, in conjunction with midline shift, an evolution of cerebral edema, increased serum SP levels, enhanced SP immunoreactivity and increased albumin extravasation." (PMID 31338013, 2019). "For 30-day to 5-year mortality, aging, stroke history, normal baseline renal function with AKI and impaired renal function with AKI were independent risk factors, while albumin level, β-blocker therapy and PCI were identified to be independent protective factors." (PMID 29299948, 2018). "Moreover, a low serum albumin level is one of the predictive factors for a first-ever non-embolic stroke in older individuals." (PMID 26757706, 2016). "This is despite evidence that albumin concentrations are lower in chronic stroke compared to non-stroke controls, indicating that protein intake is inadequate, which could lead to loss of muscle tissue." (PMID 26973796, 2015).